Y_RNA (Y RNA )
Gene: Miscellaneous RNA gene on chromosome 1 (35,195,969 to 35,196,062, forward strand). Ensembl gene ENSG00000201868.
Homologues: Orthologues: chimpanzee Y_RNA (100% identical). Paralogues in human: Y_RNA (91% identical), RNY3 (90% identical), Y_RNA (90% identical), Y_RNA (89% identical), RNY3P1 (88% identical), Y_RNA (88% identical), Y_RNA (87% identical), RNY3P14 (86% identical), Y_RNA (86% identical), RNY3P16 (85% identical), Y_RNA (85% identical), RNY3P11 (84% identical), and 95 more.